DPYS (dihydropyrimidinase)
Description:
Catalyzes the second step of the reductive pyrimidine degradation, the reversible hydrolytic ring opening of dihydropyrimidines. Can catalyze the ring opening of 5,6-dihydrouracil to N-carbamyl-alanine and of 5,6-dihydrothymine to N-carbamyl-amino isobutyrate.
Synonyms: DHP; DHPase
Tractability: No criterion of Open Targets' tractability assessment is met for any kind of drug.
Target class: Enzyme; Hydrolase
Safety:
Unwanted effects reported when the protein is acted on. In parentheses: how it was acted on, where the effect was seen, and who reports it.
drug toxicity (source: ClinPGx)
hyperglycemia (source: ClinPGx)
Gene: Protein-coding gene on chromosome 8 (104,329,333 to 104,467,111, reverse strand). Ensembl gene ENSG00000147647.
Pathways (Reactome):
Metabolism: Pyrimidine catabolism
Gene Ontology:
Molecular function: dihydropyrimidinase activity; protein binding; identical protein binding; zinc ion binding; hydrolase activity; hydrolase activity, acting on carbon-nitrogen (but not peptide) bonds; phosphoprotein binding
Biological process: pyrimidine nucleobase catabolic process; uracil catabolic process; thymine catabolic process; CMP catabolic process; dCMP catabolic process; dUMP catabolic process; UMP catabolic process
Cellular component: extracellular exosome; cytosol; cytoplasm
Genetic constraint (gnomAD): Loss-of-function variants: 39 observed, 49.5 expected, observed/expected ratio (o/e) 0.79, 90% interval 0.61 to 1.03. The upper end of that interval is the gene's LOEUF score, 1.03, which puts it in group 4 of 6, group 1 being the genes least tolerant of losing a copy. Missense variants: 657 observed, 666.9 expected, observed/expected ratio (o/e) 0.99, 90% interval 0.92 to 1.05. Synonymous variants: 245 observed, 234.5 expected, observed/expected ratio (o/e) 1.04, 90% interval 0.94 to 1.16.
Homologues: Orthologues: chimpanzee DPYS (99% identical), macaque DPYS (98% identical), dog DPYS (93% identical), pig DPYS (92% identical), mouse Dpys (88% identical), rabbit DPYS (86% identical), rat Dpys (86% identical), guinea pig DPYS (83% identical), tropical clawed frog dpys (77% identical), zebrafish dpys (72% identical), Drosophila melanogaster CRMP (56% identical), Caenorhabditis elegans dhp-2 (55% identical), and 1 more. Paralogues in human: DPYSL2 (59% identical), DPYSL3 (59% identical), CRMP1 (58% identical), DPYSL5 (58% identical), DPYSL4 (56% identical).
Diseases named in the same sentence as DPYS in open-access papers:
DPYS is named in the same sentence as 21 diseases in open-access papers, as found by Europe PMC text mining. Sharing a sentence is not in itself a finding about the gene and the disease. The quoted sentences say what the papers report.
dihydropyrimidinase deficiency (7 papers, 2015 to 2025). "Compound heterozygous or homozygous mutations in the DPYS gene have been reported in dihydropyrimidinase deficiency (OMIM #222748)." (PMID 32600357, 2020). "Mutations in the DPYS gene have been implicated in dihydropyrimidinase deficiency (OMIM #222748), a very rare autosomal recessive condition characterised by accumulation of dihydrouracil and dihydrothymine in the urine, blood and cerebrospinal fluid." (PMID 30705363, 2019). "Notably, AGXT2 and DPYS are involved in pyrimidine catabolism and are known markers of dihydropyrimidinase deficiency." (PMID 41228357, 2025). "We previously discovered a DSH cat with sporadic dihydropyrimidinase deficiency (OMIA 001776-9685), homozygous for a missense mutation (DPYS:c.1303G>A)." (PMID 40869986, 2025).
breast carcinoma (5 papers, 2008 to 2022). "Compared to adjacent normal breast, all 6 genes except NKX2-5 showed higher methylation in breast cancer by t-test analysis (P<0.001 for DPYS and EGFR5 P = 0.01 for SLC16A12; P = 0.002 for TOX; P = 0.003 for GALR2)." (PMID 18446232, 2008). "Finally, SLC16A12, GALR2, TOX, SPOCK2, EGFR5 and DPYS are candidate biomarkers for breast cancer (methylation range 33%–79%) with the combination of EGFR5 or TOX hypermethylation showing a sensitivity of 92% and specificity of 92%." (PMID 18446232, 2008). "The role of DPYS, or dihydropyrimidinase, in the hematopoietic system is currently unknown, and it may simply be a marker of methylation defects in CML as is the case in prostate and breast cancer." (PMID 21760961, 2011).
prostate carcinoma (5 papers, 2008 to 2016). A carcinoma that arises from epithelial cells of the prostate gland. "We thus confirmed the previously published DPYS hypermethylation in colon carcinomas (and breast and prostate carcinomas) compared with paired normal tissues from the same patients." (PMID 27733154, 2016). "Assays measuring methylation of MAL, TIG1, HSPB1, CCND2, and DPYS have potential to accurately stratify early prostate cancers and thereafter to manage affected patients in a biologically appropriate manner." (PMID 25193387, 2014). "Although aberrant methylation of DPYS has been reported by us and others this is the first report demonstrating its prognostic value in prostate cancer." (PMID 25193387, 2014). "In the comprehensive multivariate analysis, the model with best prognostic ability included Gleason score, PSA, HSPB1, [HSPB1xGleason score], CCND2 and DPYS demonstrating that gene methylation added significant information for predicting prostate cancer-related death." (PMID 25193387, 2014). "Among epigenetic biomarkers, most reports indicate GSTP1 hypermethylation as the diagnostic marker for prostate cancer; however, NKX2-5, CLSTN1, SPOCK2, SLC16A12, DPYS, and NSE1 also have been reported to be regulated by methylation mechanisms in prostate cancer." (PMID 24213111, 2011). "Our findings support the original hypothesis that methylation status of six selected index genes (HSPB1, CCND2, TIG1, DPYS, PITX2, and MAL) provides a novel, objective, and accurate prediction of death from prostate cancer in men clinically assessed as low to intermediate risk." (PMID 27708246, 2016). "Recently, it was reported that differential methylation of DPYS (and heat shock 27 kDa protein 1, HSPB1, OMIM: 602195 and cyclin D2, CCND2, OMIM: 123833) provides independent prognostic information for prostate carcinoma." (PMID 27733154, 2016). "In a recent report, we demonstrated that changes in methylation of HSPB1, CCND2, TIG1, DPYS, and, MAL, had significant prognostic effects in multivariate Cox models where death from prostate cancer was the study endpoint." (PMID 27708246, 2016). "Methylation was quantified by pyrosequencing assays for six genes (HSPB1, CCND2, TIG1, DPYS, PITX2, and MAL) with established biomarker value in prostate cancer." (PMID 27708246, 2016). "A model including PSA, and methylation of DPYS, HSPB1, MAL and TIG1 was better at predicting prostate cancer-related mortality than a model based only on gene methylation." (PMID 25193387, 2014). "Based on methylation in primary tumors compared to normal adjacent tissues, NKX2-5, CLSTN1, SPOCK2, SLC16A12, DPYS and NSE1 are candidate biomarkers for prostate cancer (methylation range 50%–85%)." (PMID 18446232, 2008). "Compared to adjacent normal prostate, all 8 genes had significantly higher methylation in prostate cancer by t-test analysis (P<0.001 for NKX2-5; P<0.001 for SPOCK2; P = 0.004 for GALR2; P<0.001 for CLSTN1; P<0.001 for NSE1; P<0.001 for DPYS; P = 0.019 for FOXN4; P<0.001 for SLC16A12)." (PMID 18446232, 2008). "The combination of DPYS or NSE1 hypermethylation showed a sensitivity of 80%, specificity of 95% and accuracy of 95% and the combination of NSE1 or SPOCK2 hypermethylation showed a sensitivity of 80%, specificity of 95% and accuracy of 96% in differentiating prostate cancer from normal." (PMID 18446232, 2008). "However, multivariate analysis revealed that methylation of DPYS, CCND2 and HSPB1 together added a substantial amount of prognostic information not captured by any other measure and therefore may be useful for improvement of prostate cancer management." (PMID 25193387, 2014).
colon carcinoma (2 papers, 2008 to 2016). "In a panel of 20 colon cancer cases, all these genes except IRX5, TFAP2E and TFAP2C showed significantly higher methylation in cancer by t-test analysis (P<0.001 for NKX2-5, DPYS SPOCK2, GALR2 and SLC16A12; P = 0.008 for FOXN4)." (PMID 18446232, 2008). "Similarly NKX2-5, SPOCK2, SLC16A12, DPYS and GALR2 are candidate biomarkers for colon cancer (methylation range 60%–95%) and GALR2 hypermethylation showed a sensitivity of 85% and specificity of 95%." (PMID 18446232, 2008).
cervical cancer (1 paper, 2018). A primary or metastatic malignant neoplasm involving the cervix. "LINE-1, HS3ST2, CCNA1, EPB41L3, EDNRB, LMX1, and DPYS were hypermethylated in cervical cancer tissues, CIN III and CIN II, versus normal tissues and CIN I, of which EPB41L3 seems to be the best marker." (PMID 29850477, 2018).
colorectal cancer (1 paper, 2016). A primary or metastatic malignant neoplasm that affects the colon or rectum. "DPYS and UPB1 protein levels were analyzed in a subset of the testing set used for the methylation study, enabling an evaluation of the cascade of methylation, gene, and protein expression levels in colorectal cancer samples." (PMID 27733154, 2016).
colorectal tumors (1 paper, 2016). "Moreover, promoter of the 5-FU inactivating enzyme DPYS was found hypermethylated in colorectal tumors by this study." (PMID 27733154, 2016).
developmental delay (1 paper, 2016). "Patient U2 had mutations in DPYS, which are associated with abnormal purine and pyrimidine metabolites but not with dysplastic kidneys, eczema, microcephaly and developmental delay." (PMID 27604308, 2016).
leukemia (1 paper, 2011). A malignant (clonal) hematologic disorder, involving hematopoietic stem cells and characterized by the presence of primitive or atypical myeloid or lymphoid cells in the bone marrow and the blood. "DPYS, NPM2, OSCP1, PDLIM4 and TFAP2E genes were found hypermethylated, and CDKN2B (p15INK4B) homozygously deleted in the K562 leukemia cell line." (PMID 21760961, 2011).
stomach cancer (1 paper, 2023). "According to studies, the DPYS subtype DPYSL3 was a potential biomarker for stomach cancer’s malignant nature." (PMID 37999212, 2023).
cancer (9 papers, 2008 to 2025). A tumor composed of atypical neoplastic, often pleomorphic cells that invade other tissues. "Dihydropyrimidinase (Dpys) is a key enzyme in the pyrimidine synthesis pathway and is implicated in various cancers." (PMID 41488750, 2025). "For instance, the GAD2, AOC2 and DPYS had the hypermethylation in more than most of human cancers; on the contrary, most of βAMRGs showed the hypomethylation in more than most of human cancers." (PMID 38637116, 2024). "Stepwise Cox regression modelling suggested that the methylation of genes HSPB1, CCND2 and DPYS contributed objective prognostic information to Gleason score and PSA with respect to cancer-related death during follow-up (p = 0.006)." (PMID 25193387, 2014).
tumor (5 papers, 2016 to 2025). "Significantly elevated methylation level of DPYS was recorded in tumor tissues compared to adjacent mucosa in both sets." (PMID 27733154, 2016). "Our data complies with the results reported by this database, i.e., the highest levels in UPP2, UPB1, and DPYS (the rest of the genes below 25 %) and significantly higher methylation of DPYS in tumor compared with mucosa tissues." (PMID 27733154, 2016). "DPYS methylation level was associated with the tumor stage in the testing set (P = 0.010, data not shown), but not in the validation set II." (PMID 27733154, 2016). "Ultimately, AGXT2, DPYS, and TNFSF8 were selected as HCC-specific epigenetic–transcriptomic gene markers that reflect significant differences in the tumor microenvironment, exhibiting distinct cell type specificity." (PMID 41228357, 2025). "The results showed that the expression levels of ADK, ADSL, ATIC, DPYS, ENTPD2, TXNRD1, and UCK2 in at least one tumor cell line were consistent with the predictions." (PMID 37999212, 2023). "The present study shows for the first time that only three (DPYS, UPB1, and UPP2) out of 15 evaluated 5-FU genes, are subject to notable methylation in tumor and adjacent mucosa tissues." (PMID 27733154, 2016). "In the both testing and validation II sets, methylation exceeding the limit of quantitation was detected in DPYS, UPB1, and uridine phosphorylase (UPP2, GeneID: 151531) genes in both tumor and adjacent mucosa samples (DPYS passed the correction for multiple testing)." (PMID 27733154, 2016).
metabolic disease (2 papers, 2020 to 2024). A congenital disorder (due to inherited enzyme abnormality) or acquired (due to failure of a metabolically important organ) disorder resulting from an abnormal metabolic process. "Dihydropyrimidinase (DHP) deficiency is a metabolic disease which is very rare and mutations in the DPYS gene can be the causative reason." (PMID 32600357, 2020).
DPYS also shares sentences with these, for which no sentence is quoted: diabetes (2 papers); 3-methylglutaconic aciduria type 1 (1); Alzheimer disease (1); eczema (1); microcephaly (1); mitochondrial DNA depletion syndrome 1 (1); pancreatic cancer (1); rheumatic disease (1).